IL15 (interleukin 15)
Diseases named in the same sentence as IL15 in open-access papers (continued):
Sharing a sentence is not in itself a finding about the gene and the disease.
Arthritis (18 papers, 2005 to 2026). Inflammation of a joint. "But perhaps more significantly, in consideration of the contribution of IL15 in bone resorption and inflammation, IL15 inhibition will also apply to Staphylococcus aureus-induced arthritis, which can cause rapid joint destruction and disabling joint damage despite antibiotics utilization." (PMID 32536957, 2020). "In general, from studies using human patient data and animal models of alphaviral arthritis, acute alphaviral-induced arthritis is hallmarked by increased levels of IFNα/β, IFNγ, TNFα, IL-6, IL-1, IP-10, IL-12, IL-15 and CXCL9MCP-1 (CCL2), and MIF-I." (PMID 41442410, 2026). "Overall, our results demonstrated that selectively avoiding IL-15 signaling through the trimeric IL-15Rα/IL-2Rβ/γc receptor is important for reducing inflammation in the collagen-induced arthritis model." (PMID 35592318, 2022). "Neutralization of this cytokine diminished arthritis in animal models and patients with RA, and agents blocking IL-15 were shown to be effective in clinical trials." (PMID 32455601, 2020). "We have both previously and in the present study shown that the inhibition of IL-15 reduces the number of osteoclasts in the joint and the subsequent bone destruction during S. aureus-induced arthritis." (PMID 29440371, 2018). "Previous studies have also shown elevated IL-15 mRNA expression in patients with C. trachomatis-induced arthritis compared to healthy controls." (PMID 18628987, 2008). "We therefore hypothesized that IL-15 might represent a beneficial treatment target to combine with antibiotics in the treatment of S. aureus-induced arthritis." (PMID 29440371, 2018). "IL-15 inhibition added to antibiotic treatment does not adversely affect the systemic infection and systemic bone loss in S. aureus-induced arthritis." (PMID 29440371, 2018). "The aim of the present study was to investigate whether the addition of anti-IL-15 antibodies to antibiotics could improve the outcome of S. aureus-induced arthritis compared to antibiotic treatment alone." (PMID 29440371, 2018). "IL-15 contributes to the pathogenesis of arthritis by maintaining the activation of synovial macrophages which in turn are responsible for the production and release of most proinflammatory factors, including IL-15 itself." (PMID 24223832, 2013). "In fact, IL-15 neutralization improves arthritis in animal models and patients with RA." (PMID 22242124, 2011). "IL-15 produces a number of effects which may be relevant to the pathogenesis of arthritis including recruitment and activation of T lymphocytes into the synovial membrane and induction of TNFα production." (PMID 18234077, 2008). "Furthermore, a significant correlation between IL-15 serum levels and the expression of mIL-15 on PB monocytes was observed in patients with early arthritis (I Gonzalez-Alvaro, AM Ortiz and Dominguez-Jimenez C, unpublished observation)." (PMID 16684368, 2006). "In the corresponding OMIM text, IL15 is associated with the keywords 'autoimmun', 'inflam', 'T cell', 'lymphocyte', 'antigen', 'cytokine' and 'infecti', but not 'arthritis'." (PMID 15899035, 2005). "Therefore, the objective of this work is to analyse whether serum IL-15 (sIL-15) levels serve as a biomarker of disease severity in patients with early arthritis (EA)." (PMID 22242124, 2011). "We have previously shown that interleukin-15 (IL-15) inhibition without antibiotics is beneficial in S. aureus-induced arthritis." (PMID 29440371, 2018). "Inhibition of IL-15 with antibiotic treatment reduces synovitis and bone erosions but not cartilage destruction in S. aureus-induced arthritis." (PMID 29440371, 2018). "Inhibition of IL-15 combined with antibiotic treatment did not significantly affect the clinical severity or frequency of arthritis (data not shown), bacterial clearance, weight loss, or mortality during the infection compared to antibiotics with control antibodies." (PMID 29440371, 2018).
Arthritis (continued). "The levels of IL-2, IL-12p40, IL-12p70, and IL-15, as well as those of IL-10 and IL-13, did not increase in the setting of CFA-induced arthritis." (PMID 36293292, 2022). "Notably, a mutant IL-15 construct with impaired ability to bind IL-2Rβ (NANTIL-15) selectively blocked IL-15 signaling via the trimeric IL-15Rα/IL-2Rβ/γc receptor and reduced inflammation in a collagen-induced arthritis model, without inhibiting NK or CD8+ T cell homeostasis." (PMID 38919611, 2024).
gastric cancer (18 papers, 2014 to 2026). A primary or metastatic malignant neoplasm involving the stomach. "NKG2D extracellular domain assembles with human IL-15 to form a fusion protein, dsNKG2D-IL-15, which helps NK cells infiltrate gastric cancer tissues and inhibit the growth of gastric cancer in mice." (PMID 39309440, 2024). "High concentrations of IL-15 secreted by gastric cancer MSCs contribute to tumor cell metastasis; increased IL-17 levels promote gastric cancer invasiveness." (PMID 32340207, 2020). "γδ T cells were directly isolated from the peripheral blood of gastric cancer patients (defined as peripheral-derived γδ T cells) and cultured with irradiated autologous PBMCs in the presence of IL-2 and IL-15." (PMID 24741609, 2014). "The expression of IL15 is a type of ramification in gastric cancer mesenchymal stem cells." (PMID 34211976, 2021). "CAR-T cells with an IL-15/IL-15Rα sushi domain displayed enhanced anti-tumor efficacy compared with conventional CAR-T, and GLIRP1 knockdown in gastric cancer further promoted the function of CAR-T cells." (PMID 38368374, 2024). "In this study, we constructed a new CAR structure with an IL-15/IL-15Rα sushi domain (CAR-ss-T) on the CAR extracellular region, which facilitate cytotoxicity against gastric cancer cells compared with conventional CAR." (PMID 38368374, 2024). "Recombinant mouse IL-15 (rmIL-15) facilitates NK cell proliferation and produces more IFN-γ to improve survival and inhibit liver metastasis in an inhibited gastric cancer mouse model." (PMID 39309440, 2024). "Furthermore, gastric cancer (GC)-MSCs-derived IL-15 is reported to promote EMT of GC cells via STAT3 activation." (PMID 35842634, 2022). "Phase II trial of PD-L1-CAR-NK cell immunotherapy, in combination with an IL-15 agonist (N-803) and pembrolizumab (NCT04847466), is currently underway among patients with head and neck cancers and gastric cancers in the United States." (PMID 36612114, 2022). "CAR-T cells constructed with IL-15/IL-15Rα (CAR-ss-T) showed significantly improved CAR-T cell expansion, cytokine production and cytotoxicity, and resulted in superior tumor control compared to conventional CAR-T cells in gastric cancer." (PMID 38368374, 2024). "Interestingly, the levels of P.copri and P. acnes are reportedly increased in gastric cancer patients, affecting the occurrence and development of gastric cancer through the NKG2D system and IL-15." (PMID 35093110, 2022). "Besides, after co-culture with gastric cancer cell HGC27, the percentage of total CD8+ T cells and CAR+ T cell in CD8+ T cells was not changed significantly in CAR-ss-T, suggesting the existence of IL-15/IL-15Rα did not affect the proportion of CD8+ and CD4+ T cells." (PMID 38368374, 2024).
inflammatory bowel disease (18 papers, 2015 to 2025). A spectrum of small and large bowel inflammatory diseases of unknown etiology. "Accumulating evidence indicates that inflammatory diseases of other systems, such as osteoarthritis, chronic pancreatitis, and inflammatory bowel disease, are also mediated by IL-15." (PMID 35783134, 2022). "The proteomics data and insights obtained in this study will serve as an important resource, not only for the study of IEL in CeD, but also in the context of infection, inflammatory bowel diseases and cancer, where IL-15 is overexpressed." (PMID 34257288, 2021). "Although there is little information on the role of IL-15 on TREG cells, a recent account reveals that gut-resident T cells depend on IL-15 to enhance Foxp3 over RORγT expression and block a Th17-driven inflammatory bowel disease." (PMID 30949175, 2019). "Conversely, IL-15 is a pro-inflammatory cytokine and plays a primary role in the development of autoimmune diseases and inflammatory diseases such as rheumatoid arthritis, sarcoidosis, inflammatory bowel disease." (PMID 26600079, 2015). "For example, IL-15 is overexpressed in the intestinal areas of patients with inflammatory bowel disease (IBD)." (PMID 38106519, 2023). "In chronic inflammatory conditions such as celiac disease (CeD) and inflammatory bowel disease (IBD), persistent IL-15 production by IECs induces major functional changes in T-IELs." (PMID 40005486, 2025). "Activation of NK and CD8+ cells induced by IL-15-mediated recruitment is responsible of promoting antitumor immunity and IL-15-induced T-cell activation promotes the production of pro-inflammatory cytokines such as IFNγ and TNF in inflammatory bowel diseases." (PMID 39193325, 2024). "Here we investigate how a pleiotropic cytokine interleukin (IL)-15 may modify the functional commitment of CD4+ T cells expressing the lineage-associated transcription factors: forkhead box P3 (Foxp3; Treg) and RORγt (Th17) in the context of inflammatory bowel disease (IBD)." (PMID 26964669, 2016).
metastatic melanoma (18 papers, 2016 to 2025). A melanoma that has spread from its primary site to another anatomic site. "Similar immune activation trends were reported in a phase I clinical trial using inhaled recombinant human IL-15 in dogs with metastatic melanoma or osteosarcoma, where cytokine induction and increased PBMC cytotoxicity correlated with clinical benefit." (PMID 40552079, 2025). "A phase I clinical trial of recombinant human IL‐15 infusion evaluated in patients with metastatic melanoma and renal cell cancer demonstrated significant changes in NK, γδ and CD8 memory T cells." (PMID 38887915, 2024). "Targeting cytokines such as IL-6 and IL-15 is currently being evaluated in clinical trials in combination with immune checkpoint-blocking antibodies for the treatment of metastatic melanoma." (PMID 38928238, 2024). "A phase I trial of recombinant IL-15 in adults with refractory metastatic malignant melanoma and metastatic cancer also demonstrated that IL-15 increased the activity of NK and CD8 T cells." (PMID 35127700, 2021). "IL15 has entered the clinical trial in patients with metastatic melanoma, renal cell carcinoma, and non-small cell lung cancer in CAR-T therapy and combination treatment with anti-PD1 antibody." (PMID 33381115, 2020). "A recent clinical trial employing Escherichia coli-produced rhIL-15, administered to patients with metastatic malignant melanoma or metastatic renal cell cancer, demonstrated safety of IL-15 treatment of patients with metastatic malignancy." (PMID 30601063, 2019). "IL-15 has been reported as tolerable for use in patients with metastatic melanoma or metastatic renal cell carcinoma, with patients showing altered homeostasis of NK cells, γδ T cells and CD8+ T cells in peripheral blood after treatment." (PMID 30670085, 2019). "Finally, given that combined inhibition of BRAF/MEK is associated with improved clinical outcomes among patients with BRAF V600-mutated metastatic melanoma, we further assessed whether the addition of IL-18 to IL-15 was also able to rescue NK suppression induced by BRAF/MEK co-inhibition." (PMID 27563819, 2016). "Adoptive transfer of tetramer+ CD8+ T cells was significantly more effective in prolonging survival in IL-15-treated than in control mice bearing metastatic melanoma." (PMID 26824989, 2016). "Therefore, we investigated the ability of both free and complexed CD11c-restricted IL15 to inhibit lung metastasis in a model of metastatic melanoma." (PMID 26822794, 2016). "Finally, a short incubation of MART-1-specific T cells with rapamycin acted synergistically with IL-15, leading to significantly improved tumor-free survival in recipients with metastatic melanoma." (PMID 26824989, 2016). "In clinical trials, human IL15 as monotherapy promoted proliferation of circulating NK cells and CD8 T cells in patients with metastatic melanoma and renal cancer, with the cost of severe toxicity at the therapeutic dose." (PMID 33381115, 2020). "Notably, a powerful antitumor response leading to 100% survival for more than 300 days was seen in IL-15-treated mice infused with Rapa-T cells, while most of the mice receiving Rapa-T cells without IL-15 and half of the IL-15-treated mice receiving Ctrl-T cells succumbed to metastatic melanoma." (PMID 26824989, 2016). "The first in-human clinical trial employing recombinant human IL-15 (rhIL-15) in patients with metastatic melanoma and renal cell cancer (RCC) showed that administration of IL-15 is safe and that can enhance the function and proliferation of NK cells in peripheral blood of cancer patients." (PMID 38077389, 2023). "Subsequently, we investigated the correlation between increased intra-tumoral IL-15 expression in stage IV with the plasmatic levels of the sIL-15/IL-15R complex in non-lympho-depleted metastatic melanoma patients." (PMID 37334356, 2023).
metastatic melanoma (continued). "These preclinical data have provided important evidence for the use of IL-15 in the treatment of AML and have suggested that IL-15 may also be effective for the treatment of metastatic melanoma." (PMID 30813924, 2019). "The data support the idea of using IL-15 to enhance antitumor responses of adoptive T-cell transfer therapy, and a clinical trial launched recently to test the effectiveness of TIL administration combined with IL-15 in metastatic melanoma." (PMID 26824989, 2016).
B-cell lymphoma (16 papers, 2016 to 2025). "The most encouraging results came from the phase I/II clinical trial where cord blood (CB) derived iC9/CAR.19/IL15 CB-NK cells were used for treating refractory B-cell lymphoma or leukemia (ClinicalTrials.gov Identifier: NCT03056339)." (PMID 35806311, 2022). "Regarding hematological malignancies, in clinical trials of anti-CD19 CAR-T cell therapy for R/R B cell lymphoma, the concentration of IL-15 after CAR-T cell infusion was a strong predictor of the patients’ prognosis." (PMID 32616000, 2020). "In this respect, Moga and colleagues showed that IL-15 or CpG ODN can enhance rituximab-induced ADCC against B-cell lymphoma." (PMID 27713158, 2016). "Furthermore, inducing NK cells with a memory-like phenotype by briefly activating them with a cytokine cocktail of IL-12, IL-15 and IL-18 can lead to cytokine-induced memory-like NK cells, which show enhanced responses against NK-resistant B-cell lymphoma." (PMID 35453554, 2022). "Currently, the IL-15 fusion protein ALT-803, in combination with rituximab, is being tested in a clinical trial in patients with indolent B cell non-Hodgkin lymphoma (NCT02384954)." (PMID 34681717, 2021). "treated B-cell lymphoma by constructing UCB-derived CAR NK cells carrying IL15 cytokine targeting CD70, and found that carrying IL15 could promote the survival of CAR NK cells in vivo." (PMID 41246355, 2025). "The IL-15 superagonist/IL-15Rα-Fc fusion complex (designated ALT-803) has previously been shown to enhance NK lysis of tumor cells and to augment NK-cell ADCC of B cell lymphomas directed by rituximab." (PMID 29088859, 2017). "IL-15, while not able to protect NK cells alone, enhanced the recovery and function of cryopreserved NK cells when used in combination with IL-18, achieving equipotency in a cytotoxicity assay, and in vivo in a model of disseminated B-cell lymphoma." (PMID 38729924, 2024).
Insulin resistance (16 papers, 2012 to 2024). Increased resistance towards insulin, that is, diminished effectiveness of insulin in reducing blood glucose levels. "IL-15 is a proinflammatory cytokine implicated in the development of insulin resistance and hepatic steatosis." (PMID 38455231, 2024). "It is well known that weight loss reduces insulin resistance and improves glucose homeostasis, whereas IL-15 might improve glucose regulation in hyperglycemic obese animals." (PMID 31772933, 2019). "Indeed our findings on IL-15-deficient mice maintained on high-fat diet show that IL-15 is required for diet-induced weigh-gain, steatosis, insulin resistance and inflammation." (PMID 27684068, 2016). "High levels of IL-15 contribute to the improvement of insulin resistance in postmenopausal women with metabolic syndrome." (PMID 37876013, 2023). "In mice, high levels of circulating IL-15 prevented abnormal glucose tolerance and insulin resistance induced by the high-fat diet." (PMID 36467072, 2022). "Using IL-15 to amplify AT-NK and to promote an anti-tumor effect also aggravated inflammation and insulin resistance in adipose tissues." (PMID 34421909, 2021). "The aim of our study was to assay circulating interleukin-15 (IL-15) and interleukin-6 (IL-6) levels and insulin resistance measured by two different methods in newly diagnosed autoimmune diabetes (AD) patients, their I° relatives, and healthy controls." (PMID 31772933, 2019). "On the other hand, muscle waste results in the decrease in the production of IL-15, which plays an important role in inhibiting adipose tissue and reversing insulin resistance, and the proliferation and development of natural killer (NK) cells." (PMID 29740069, 2018). "IL-15 inhibits fat deposition and insulin resistance, is anabolic for skeletal muscle in certain situations, and is required for the development and survival of natural killer (NK) lymphocytes." (PMID 22935594, 2012). "IL-15 and IL-6 are cytokines secreted by skeletal muscle cells, addition to the immune cells during immune responses, and are involved in the pathogenesis of autoimmune diseases and insulin resistance." (PMID 37876013, 2023). "The aim of our study was to assay circulating IL-15 and IL-6 levels in patients with newly diagnosed AD, their first-degree relatives, and healthy controls in comparison with the presence of anti-islet antibodies and insulin resistance." (PMID 31772933, 2019). "Administering IL-15 to expand NKs increases the number of VAT-M1s and exaggerates VAT inflammation and insulin resistance." (PMID 34421909, 2021). "A positive correlation between IL-15 and HOMAIR and negative correlation with eGDR suggest that IL-15 also potentially affects insulin resistance." (PMID 31772933, 2019). "Therefore, it is likely that the beneficial effect of exercise may be mediated by other factors like Irisin or Meteorin-like hormone that are also produced by muscles and help to reduce insulin resistance, rather than by IL-15." (PMID 27684068, 2016).
renal cell carcinoma (16 papers, 2012 to 2024). "Another study investigated the use of adoptive cell therapy with IL-15-induced γδT cells in a patient-derived renal cell carcinoma xenograft model." (PMID 38077392, 2023). "Consistently, the Tpex subset of PD-1+ CD8 TILs from human renal cell carcinoma (RCC) tumors also had a superior ability to proliferate following ex vivo IL-15 treatment, compared with the Ttex subset." (PMID 37409128, 2023). "Trials combining IL-15 with avelumab (anti-PD-L1) are also underway in patients with renal cell cancer and mature T-cell lymphoma." (PMID 37465665, 2023). "The ability of Interleukin-15 (IL-15) to activate many immune antitumor mechanisms renders the cytokine a good candidate for the therapy of solid tumors, particularly renal cell carcinoma." (PMID 22363690, 2012). "In addition, we assessed the responsiveness of CD8 tumor-infiltrating lymphocytes (TILs) from renal cell carcinoma patients to IL-15." (PMID 37409128, 2023). "The first human clinical trial of IL-15 showed that NK and CD8+ T cells were amplified in STIE (peripheral blood) of patients with advanced melanoma and patients with renal cell carcinoma (RCC), but with severe adverse reactions." (PMID 35799264, 2022).